POLRMT (RNA polymerase mitochondrial)
Diseases named in the same sentence as POLRMT in open-access papers (continued):
Sharing a sentence is not in itself a finding about the gene and the disease.
mitochondrial disease (4 papers, 2021 to 2026). "This study expands the genetic and phenotypic landscape of mitochondrial disease associated with POLRMT variants." (PMID 40583167, 2026). "Here, the authors identify mutations in POLRMT in individuals with mitochondrial disease-related phenotypes and characterise underlying defects in mitochondrial transcription." (PMID 33602924, 2021). "In summary, we report the identification of pathogenic variants in the mitochondrial RNA polymerase, POLRMT, that underlie the mitochondrial disease-associated phenotypes present in the seven families we have studied." (PMID 33602924, 2021). "Here, we report the clinical and genetic characteristics of six new patients from six unrelated families, thus expanding the clinical and genetic spectrum of POLRMT‐related mitochondrial disease." (PMID 40583167, 2026). "We identified potentially damaging monoallelic and biallelic POLRMT variants in affected individuals from six unrelated families, thus extending both the clinical and genetic phenotypes of POLRMT‐related mitochondrial disease." (PMID 40583167, 2026). "Diseases caused by POLRMT and TEFM mutations are similar and a wide variety of features overlap with other mitochondrial diseases, establishing defective mitochondrial transcription elongation as an important disease mechanism." (PMID 36823193, 2023). "The majority of the core proteins of the mtDNA replication and expression machinery are dedicated mitochondrial proteins, with pathological variants resulting solely in mitochondrial disease phenotypes, including POLG, POLG2, TWINKLE, MGME1 and POLRMT." (PMID 37013609, 2023). "Our data demonstrate that defective POLRMT can lead to classical mitochondrial disease and wider neurological manifestations which are independent of disordered mtDNA maintenance." (PMID 33602924, 2021). "POLRMT is key for transcription of the mitochondrial genome, yet has not been implicated in mitochondrial disease to date." (PMID 33602924, 2021). "In contrast, pathogenic variants in POLRMT have not, until now, been associated with mitochondrial disease." (PMID 33602924, 2021).
neurological disease (2 papers, 2021 to 2023). "In addition, there is a study reported eight patients with POLRMT mutations associated with mitochondrial dysfunction and neurological disorders." (PMID 37860673, 2023).
autosomal dominant disease (1 paper, 2021). Autosomal dominant form of disease. "The clinical presentation of POLRMT mutations is variable and there is no clear distinction between autosomal recessive and autosomal dominant disease." (PMID 33602924, 2021).
infection (1 paper, 2015). The state of being infected such as from the introduction of a foreign agent such as serum, vaccine, antigenic substance or organism. "shRNA delivery of sequences directed against POLRMT was achieved using lentiviral infection in OCI-AML2 cells." (PMID 26484416, 2015).
POLRMT also shares sentences with these, for which no sentence is quoted: B cell lymphoma (1 paper); development (1); diabetes mellitus (1); diffuse large B-cell lymphoma (1); glioblastoma (1); hematological malignancies (1); intellectual disabilities (1); intellectual disability syndrome (1); Leigh syndrome (1); leukodystrophy (1); lymphoma (1); multiple myeloma (1); ovarian carcinoma (1); proliferative diabetic retinopathy (1).